RCC1 (regulator of chromosome condensation 1)
Description:
Guanine-nucleotide releasing factor that promotes the exchange of Ran-bound GDP by GTP, and thereby plays an important role in RAN-mediated functions in nuclear import and mitosis. Contributes to the generation of high levels of chromosome-associated, GTP-bound RAN, which is important for mitotic spindle assembly and normal progress through mitosis. Via its role in maintaining high levels of GTP-bound RAN in the nucleus, contributes to the release of cargo proteins from importins after nuclear import. Involved in the regulation of onset of chromosome condensation in the S phase. Binds both to the nucleosomes and double-stranded DNA.
Synonyms: CHC1; IIAAN; RCC1-I
Tractability: Small molecule: a structure with a bound ligand is known; it has a high-quality binding pocket. PROTAC: ubiquitination databases record sites on it; its protein half-life has been measured.
Gene: Protein-coding gene on chromosome 1 (28,505,943 to 28,539,300, forward strand). Ensembl gene ENSG00000180198.
Subcellular location: Nucleus; Chromosome; Cytoplasm
Subcellular location (Human Protein Atlas): Nucleoplasm
Pathways (Reactome):
Disease: Nuclear import of Rev protein; Rev-mediated nuclear export of HIV RNA
Cell Cycle: Postmitotic nuclear pore complex (NPC) reformation
Gene Ontology:
Molecular function: chromatin binding; guanyl-nucleotide exchange factor activity; histone binding; nucleosomal DNA binding; nucleosome binding; protein binding; protein heterodimerization activity; small GTPase binding; sulfate binding
Biological process: chromosome segregation; G1/S transition of mitotic cell cycle; mitotic spindle organization; positive regulation of cell cycle process; regulation of mitotic nuclear division; spindle assembly; mitotic nuclear membrane reassembly; regulation of mitotic cell cycle; regulation of mitotic spindle assembly; viral process
Cellular component: chromatin; chromosome; condensed nuclear chromosome; cytoplasm; nucleoplasm; nucleus; protein-containing complex
Genetic constraint (gnomAD): Loss-of-function variants: 11 observed, 45.93 expected, observed/expected ratio (o/e) 0.24, 90% interval 0.15 to 0.4. The upper end of that interval is the gene's LOEUF score, 0.4, which puts it in group 1 of 6, group 1 being the genes least tolerant of losing a copy. Missense variants: 386 observed, 566.94 expected, observed/expected ratio (o/e) 0.68, 90% interval 0.63 to 0.74. Synonymous variants: 213 observed, 225.24 expected, observed/expected ratio (o/e) 0.95, 90% interval 0.85 to 1.06.
Homologues: Orthologues: chimpanzee RCC1 (99% identical), macaque RCC1 (99% identical), dog RCC1 (96% identical), pig RCC1 (96% identical), rabbit RCC1 (96% identical), guinea pig RCC1 (95% identical), mouse Rcc1 (94% identical), rat Rcc1 (90% identical), tropical clawed frog rcc1 (77% identical), zebrafish rcc1 (74% identical), Drosophila melanogaster Rcc1 (42% identical), Caenorhabditis elegans ran-3 (27% identical), and 1 more. Paralogues in human: HERC1 (35% identical), RCC1L (25% identical), ALS2 (23% identical), RPGR (23% identical), RCC2 (22% identical), RCBTB1 (19% identical), SERGEF (19% identical), RCBTB2 (18% identical), RCCD1 (16% identical).
Diseases named in the same sentence as RCC1 in open-access papers:
RCC1 is named in the same sentence as 63 diseases in open-access papers, as found by Europe PMC text mining. Sharing a sentence is not in itself a finding about the gene and the disease. The quoted sentences say what the papers report.
breast carcinoma (17 papers, 2008 to 2025). "Conversely, high USP53 expression, inversely regulated by RCC1, was associated with improved survival (p = 2.9e-0.05 for breast cancer, p = 1.3e-11 for lung cancer)." (PMID 40163507, 2025). "Accumulated evidence demonstrates that mutations of RCC1 were involved in tumor development, and upregulation of RCC1 played an essential role in tumor progression, such as breast cancer and ovarian cancer 13-17." (PMID 38434981, 2024). "In addition, the RCC1∗ C. 1067_1086del19 mutation found in Tunisian familial breast cancer patients also indicates that RCC1 mutations have carcinogenic potential." (PMID 33102517, 2020). "This study unveils RCC1’s pivotal role in cancer biology by silencing its expression in MDA-MB-231 (breast cancer) and A549 (lung cancer) cell lines using shRNA." (PMID 40163507, 2025). "To date, growing evidence has identified RCC1 as a factor in tumorigenesis, particularly in cervical, lung, and breast cancers." (PMID 41187218, 2025). "RCC1 can regulate the development of variety cancer, such as breast cancer, ovarian cancer and so on, so we selected RCC2 as research object for the next stage." (PMID 38434981, 2024). "Analysis in the CPTAC dataset showed that the expression of RCC1 total protein in primary tumor tissues of breast cancer, ovarian cancer, colon cancer, LUAD, RCC and UCEC was higher than that in normal tissues." (PMID 34298996, 2021). "Based on the CPTAC dataset, the differences in the phosphorylation levels of RCC1 between the six tumors (breast cancer, colon cancer, clear cell RCC, LUAD, ovarian cancer, UCEC) and the corresponding normal tissues were also analyzed." (PMID 34298996, 2021). "Furthermore, a novel truncating mutation in the RCC1 gene was found in Tunisian breast cancer patients using WES associated with genotyping, suggesting that RCC1 is a novel breast cancer susceptibility gene." (PMID 35893033, 2022). "At the same time, the pooled analysis of different studies in the Oncomine database confirmed that compared with normal tissues, RCC1 is highly expressed in lung cancer, colorectal cancer, breast cancer, bladder cancer, brain cancer, sarcoma, prostate cancer, and leukemia." (PMID 34298996, 2021). "Compared with normal tissues, the S11 locus of RCC1 showed higher phosphorylation levels in breast cancer (p < 0.001), colon cancer (p < 0.001), clear cell RCC (p < 0.001) and LUAD (p < 0.001), but not significantly in ovarian cancer (p = 0.09) and UCEC (p = 0.37)." (PMID 34298996, 2021). "Novel Ras protein-Regulator of chromosome condensation 1 (Ran-RCC1) inhibitory peptides designed to interact with Ran, a novel therapeutic target in breast cancer, were delivered by entrapment into polyethylene glycol-poly (lactic-co-glycolic acid) PEG-PLGA polymeric nanoparticles (NPs)." (PMID 30769871, 2019). "Kaplan-Meier survival analysis revealed that high RCC1 and SGOL2 expression correlated with poorer survival outcomes in breast and lung cancer patients (p = 0.00014 for breast cancer, p = 3.2e-07 for lung cancer)." (PMID 40163507, 2025). "Therefore, targeted delivery systems - such as nano-polymeric carriers, which have shown efficacy in preclinical breast cancer studies - may offer a promising approach to enhance tumor-selective uptake of RCC1 inhibitors and chemotherapeutics while minimizing adverse effects." (PMID 41281944, 2025). "Additionally, the high expression of RCC1 is also related to poor OS, relapse-free survival (RFS), distant metastasis-free survival (DMFS) and PPS in breast cancer and poor OS, RFS, disease-specific survival (DSS) and progress-free survival (PFS) in liver cancer (all p < 0.05)." (PMID 34298996, 2021).
glioblastoma (11 papers, 2021 to 2025). The most malignant astrocytic tumor (WHO grade IV). "RCC1 regulates nucleocytoplasmic transport via the RanGTP gradient, and methylation of RCC1 at R214 disrupts Ran activation and RCC1-mediated mitosis and nucleocytoplasmic transport in glioblastoma." (PMID 41281944, 2025). "It was found that expression of the RCC1 gene is upregulated in glioblastoma; the RCC1 protein predominantly resides on centrioles during metaphase." (PMID 41373435, 2025). "The results obtained expand our understanding of RCC1’s functions beyond regulation of chromatin condensation, indicating its potential role in glioblastoma pathogenesis." (PMID 41373435, 2025). "In pancreatic cancer, RCC1 silencing sensitizes tumors to gemcitabine, while in glioblastoma, methylation at arginine 214 (R214) of RCC1 reduces RanGTP levels, enhancing radiosensitivity." (PMID 41281944, 2025). "Existing studies have shown that PRMT6 is upregulated in gliomas and regulates the mitosis and tumorigenicity of glioblastoma stem cells by methylating RCC1, or promotes the proliferation of glioma cells by transcriptionally activating CDC20." (PMID 38637831, 2024). "Some studies found that PRMT6 methylation of the RCC1 signaling axis regulates mitosis, tumorigenicity, and the radiation response of glioblastoma stem cells." (PMID 34593910, 2021). "In U87MG glioblastoma cells, the RCC1 protein is localized near centrioles during mitosis." (PMID 41373435, 2025). "Besides, methylation of PRMT6 at RCC1 R214 regulates proliferation, stem-like properties, and tumorigenicity of glioblastoma stem cells by CK2α-PRMT6-RCC1 signaling axis." (PMID 40164592, 2025). "Hence, EPZ020411, a PRMT6-specific inhibitor, inhibits the methylation of the arginine residue of RCC1 to maximize the positive effects of radiotherapy in a glioblastoma xenograft model." (PMID 37394580, 2023). "In addition, PRMT6 assists in the maintenance of CSC characteristics in glioblastoma through methylation of the regulator of chromosome condensation 1 (RCC1) protein." (PMID 37394580, 2023). "In glioblastoma, CK2 was reported to phosphorylate and stabilize PRMT6, which enhances the methylation of RCC1, thereby facilitating RCC1 localization in chromatin and contributing to tumorigenicity and progression of glioblastoma." (PMID 39827153, 2025). "Previous research has revealed that in glioblastoma stem cells, PRMT6 methylation of RCC1 controls mitogenesis, tumorigenicity, and radiation sensitivity." (PMID 39528487, 2024).
gastric cancer (9 papers, 2017 to 2025). A primary or metastatic malignant neoplasm involving the stomach. "Another study showed that the high methylation level of the RCC1 gene in gastric cancer tissue caused the silence of RCC1, which induced the oncogenesis and increased development of invasion depth." (PMID 34298996, 2021). "Clinicopathologically, the loss of RCC1 expression in gastric cancer leads directly to the development of tumor differentiation and invasion depth." (PMID 33102517, 2020). "For example, the expression of RCC1 in gastric cancers and other tumors is significantly reduced, with different degrees of silencing occurring." (PMID 33102517, 2020). "Hence, RCC1 expression is significantly downregulated in gastric cancer, and different RCC1 expression suppression levels are observed." (PMID 41373435, 2025). "RCC1 is negatively correlated with the progression of lung adenocarcinoma and gastric cancer." (PMID 38561375, 2024). "This suggests RCC1 to be a tumor suppressor gene in gastric cancer." (PMID 34298996, 2021). "Another report showed that RCC1 expression was significantly lower in gastric carcinoma tissues and that the silencing of RCC1 could induce tumorigenesis and was correlated with deeper invasion in gastric cancer, indicating that RCC1 may be a tumor suppressor in gastric carcinoma." (PMID 34924821, 2021).
cervical cancer (8 papers, 2018 to 2025). A primary or metastatic malignant neoplasm involving the cervix. "Taken together, this study is the first to identify a relationship between RCC1 and cervical cancer and uncovers a novel function of RCC1 in high-risk HPV E7-mediated G1/S cell cycle control." (PMID 29789527, 2018). "Another research indicated that c-Jun directly modulate RCC1 expression level in papillomavirus-related cervical cancer." (PMID 38434981, 2024). "For example, in human papillomavirus E7-expressing cervical cancer, RCC1 is found to be upregulated and promoted tumorigenesis by abrogating the G1 cell cycle checkpoint." (PMID 38561375, 2024). "For example, RCC1 was found to be upregulated in E7-expressing epithelial cells and cervical cancer cells." (PMID 38561375, 2024). "On the other hand, RCC1 is found to be upregulated and plays oncogenic roles in many other types of cancer, such as cervical cancer and colon cancer." (PMID 38561375, 2024). "Our previous data showed that RCC1 was highly expressed in cervical cancer tissues and cells, and contributed to G1 checkpoint abrogation in HPV E7-expressing cells." (PMID 34356619, 2021). "In a study of human papillomavirus-related cervical cancer, transcription factor c-Jun directly upregulated RCC1 transcription in HPV-E7 expressing cells." (PMID 33102517, 2020). "A typical example is in cervical cancer, as based on microarray gene expression profiles, where RCC1 overexpression has only been observed in the FIGO Stage III." (PMID 33102517, 2020). "We detected a weak cytoplasmic signal for RCC1 protein in all normal cervix and cervical cancer tissues." (PMID 29789527, 2018). "We found that RCC1 mRNA expression (the probe set 206499_s_at, 215747_s_at) was upregulated in cervical cancer tissues and cell lines, including SiHa and HeLa, in comparison with normal cervical epithelium." (PMID 29789527, 2018). "Data from GEO datasets showed that RCC1 was overexpressed in cervical cancer as well as HPV-related cervical cancer." (PMID 29789527, 2018). "To confirm the function of RCC1 in the cell cycle, we treated SiHa cervical cancer cells with siRCC1s and observed downregulation of E2F1, Cdk1, and Cdk2 protein levels." (PMID 29789527, 2018). "To confirm these observations, we performed immunohistochemical staining for RCC1 protein in normal cervix (n = 11 samples) and cervical cancer tissues (n = 47 samples)." (PMID 29789527, 2018). "Eliminating these two HPV-negative samples, RCC1 expression was still significantly higher in HPV-positive cervical cancers." (PMID 29789527, 2018). "We first showed that RCC1 was upregulated by c-Jun in both cervical cancer tissues and HPV-16 E7-expressing cells." (PMID 29789527, 2018). "Whole genome expression profiling of progressive stages of cervical cancer indicated that high RCC1 expression was closely correlated with FIGO Stage III21." (PMID 29789527, 2018). "In this study, we first observed that RCC1 immunostaining was mildly increased in cervical cancer tissues and significantly upregulated in HPV E7-expressing cells; this localization was primarily nuclear." (PMID 29789527, 2018). "Elevated expression of RCC1 has been observed in cervical cancer, colon cancer, and soft tissue sarcoma, where RCC1 may play important role in nucleo-cytoplasmic trafficking of certain molecules such as Skp2 to regulate cell cycle transition and proliferation." (PMID 41391757, 2025). "In contrast, loss of RCC1 blocks the G1/S phase transition without inducing apoptosis in cervical cancer and sensitizes immunotherapy via p27Kip1/CDK4 axis." (PMID 38561375, 2024). "We next examined the regulation of RCC1 phosphorylation in cervical cancer cells." (PMID 34356619, 2021). "We speculate that E7 activates the AKT/mTOR pathway, and the latter promotes RCC1 S11 phosphorylation in cervical cancer cells." (PMID 34356619, 2021). "However, the exact role of the PI3K/AKT/mTOR activation in RCC1-induced cervical cancer development is still unclear." (PMID 34356619, 2021).
cervical cancer (continued). "Moreover, RCC1 S11 was phosphorylated by the PI3K/AKT/mTOR pathway in HPV-positive cervical cancer SiHa and HeLa cells." (PMID 34356619, 2021). "Since human papillomavirus (HPV) is the main etiologic factor in cervical cancer, we speculated that RCC1 expression was correlated with HPV infection." (PMID 29789527, 2018). "In our model, RCC1 is upregulated in cervical cancer tissues and cell lines by HPV E7." (PMID 29789527, 2018). "Furthermore, immunostaining demonstrated that RCC1 protein was slightly increased in cervical cancer tissues compared with normal cervix." (PMID 29789527, 2018). "We further confirmed the expression of RCC1 S11 phosphorylation and its regulation in HPV-positive cervical cancer SiHa and HeLa cells." (PMID 34356619, 2021). "We showed that RCC1 was strongly phosphorylated on S11 in HPV E7-expressing cells and cervical cancer cells." (PMID 34356619, 2021). "In this study, we explored the cell cycle-promoting activity of RCC1 in HPV E7-expressing epithelium and cervical cancer cells." (PMID 29789527, 2018). "However, the role of RCC1 in cervical cancer and in HPV E7-expressing cells is largely unknown." (PMID 29789527, 2018). "As shown in the NCBI GEO dataset (accession No. GDS3233), RCC1 mRNA levels were higher in cervical cancer cells, including HeLa and SiHa." (PMID 29789527, 2018). "The expression and function of RCC1 in HPV-related cervical cancer and cell cycle regulation have not yet been explored." (PMID 29789527, 2018).
colorectal cancer (5 papers, 2007 to 2025). A primary or metastatic malignant neoplasm that affects the colon or rectum. "Previous studies also showed statistically significantly higher RCC1 expression in ovarian tumors, colorectal cancer, carboplatin-resistant cervical tumors, and lung adenocarcinoma compared to normal tissues." (PMID 34924821, 2021). "In colorectal cancer, RCC1 may promote cell cycle progression by changing the E2F status, thereby affecting the progression of tumors." (PMID 34924821, 2021). "It was also reported that RCC1 promotes doxorubicin resistance in colorectal carcinoma cells." (PMID 34924821, 2021). "GD562 exhibited improved inhibition of the cellular N-terminal methylation levels of both the regulator of chromosome condensation 1 and the oncoprotein SET with an IC50 value of ~50 μM in human colorectal cancer HCT116 cells." (PMID 35209173, 2022).